MBD3L4 (methyl-CpG binding domain protein 3 like 4)
Tractability: No criterion of Open Targets' tractability assessment is met for any kind of drug.
Gene: Protein-coding gene on chromosome 19 (7,037,749 to 7,040,179, reverse strand). Ensembl gene ENSG00000205718.
Subcellular location (Human Protein Atlas): Nucleoli; Nucleoplasm; Cytosol
Gene Ontology:
Molecular function: methyl-CpG binding
Biological process: DNA methylation-dependent constitutive heterochromatin formation; negative regulation of transcription by RNA polymerase II
Cellular component: nucleus
Homologues: Orthologues: rat Mbd3l2 (43% identical), rat Mbd3l3 (40% identical), mouse Mbd3l2 (39% identical), zebrafish mbd3a (31% identical), tropical clawed frog mbd3 (30% identical), Drosophila melanogaster MBD-like (22% identical). Paralogues in human: MBD3L3 (99% identical), MBD3L5 (99% identical), MBD3L2 (98% identical), MBD3L2B (97% identical), MBD3L1 (35% identical), MBD2 (32% identical), MBD3 (31% identical), MBD1 (21% identical).